RNU6-797P (RNA, U6 small nuclear 797, pseudogene)
Gene: Small nuclear RNA gene on chromosome 7 (140,209,563 to 140,209,671, reverse strand). Ensembl gene ENSG00000199971.
Homologues: Orthologues: chimpanzee U6 (99% identical), macaque U6 (96% identical), rabbit U6 (81% identical), dog U6 (78% identical). Paralogues in human: RNU6-1209P (91% identical), RNU6-1287P (91% identical), RNU6-183P (89% identical), RNU6-879P (89% identical), RNU6-1047P (88% identical), RNU6-1083P (88% identical), RNU6-1091P (88% identical), RNU6-1094P (88% identical), RNU6-1159P (88% identical), RNU6-115P (88% identical), RNU6-669P (88% identical), RNU6-727P (88% identical), and 1288 more.